HSD3B2 (hydroxy-delta-5-steroid dehydrogenase, 3 beta- and steroid delta-isomerase 2)
Description:
3-beta-HSD is a bifunctional enzyme, that catalyzes the oxidative conversion of Delta(5)-ene-3-beta-hydroxy steroid, and the oxidative conversion of ketosteroids. The 3-beta-HSD enzymatic system plays a crucial role in the biosynthesis of all classes of hormonal steroids.
Synonyms: SDR11E2; HSD3B; HSDB
Tractability: Small molecule: an approved drug acts on it; it belongs to a druggable protein family. Antibody: UniProt predicts a signal peptide or a membrane-spanning region. PROTAC: a small molecule that binds it is known.
Target class: Enzyme; Oxidoreductase
Gene: Protein-coding gene on chromosome 1 (119,413,725 to 119,423,035, forward strand). Ensembl gene ENSG00000203859.
Subcellular location: Endoplasmic reticulum membrane; Mitochondrion membrane
Subcellular location (Human Protein Atlas): Endoplasmic reticulum; Primary cilium; Cytokinetic bridge; Microtubules; Nucleoli; Primary cilium transition zone
Pathways (Reactome):
Metabolism: Androgen biosynthesis; Glucocorticoid biosynthesis; Mineralocorticoid biosynthesis
Gene Ontology:
Molecular function: 3-beta-hydroxy-Delta5-steroid dehydrogenase (NAD+) activity; protein binding; steroid Delta-isomerase activity; alcohol dehydrogenase (NAD+) activity; oxidoreductase activity, acting on the CH-OH group of donors, NAD or NADP as acceptor
Biological process: androgen biosynthetic process; steroid biosynthetic process; C21-steroid hormone metabolic process
Cellular component: endoplasmic reticulum; endoplasmic reticulum membrane; cytoplasm; membrane; mitochondrial inner membrane; mitochondrial intermembrane space; mitochondrial membrane; smooth endoplasmic reticulum membrane
Genetic constraint (gnomAD): Loss-of-function variants: 9 observed, 10.86 expected, observed/expected ratio (o/e) 0.83, 90% interval 0.5 to 1.44. The upper end of that interval is the gene's LOEUF score, 1.44, which puts it in group 5 of 6, group 1 being the genes least tolerant of losing a copy. Missense variants: 410 observed, 467.68 expected, observed/expected ratio (o/e) 0.88, 90% interval 0.81 to 0.95. Synonymous variants: 221 observed, 193.65 expected, observed/expected ratio (o/e) 1.14, 90% interval 1.02 to 1.28.
Homologues: Orthologues: chimpanzee HSD3B2 (99% identical), macaque HSD3B2 (96% identical), dog HSD3B2 (80% identical), guinea pig Hsd3b1 (73% identical), rat Hsd3b2 (73% identical), rat Hsd3b1 (72% identical), mouse Hsd3b1 (71% identical), mouse Hsd3b2 (71% identical), mouse Hsd3b3 (70% identical), mouse Hsd3b6 (70% identical), mouse Hsd3b5 (67% identical), mouse Hsd3b4 (67% identical), and 10 more. Paralogues in human: HSD3B1 (94% identical), HSD3B7 (37% identical), SDR42E1 (31% identical), SDR42E2 (28% identical), NSDHL (25% identical), TGDS (22% identical), GALE (21% identical), UXS1 (19% identical), GMDS (18% identical), GFUS (14% identical).